RNF32-DT (RNF32 divergent transcript)
Synonyms: C7orf13; LINC01006; MY040
Gene: Long non-coding RNA gene on chromosome 7 (156,388,922 to 156,640,654, reverse strand). Ensembl gene ENSG00000182648.
Subcellular location: Cytoplasm; Membrane
Diseases named in the same sentence as RNF32-DT in open-access papers:
RNF32-DT is named in the same sentence as 8 diseases in open-access papers, as found by Europe PMC text mining. Sharing a sentence is not in itself a finding about the gene and the disease.
RNF32-DT shares sentences with these, for which no sentence is quoted: pancreatic cancer (3 papers); tumor (3); gastric cancer (2); glioblastoma (2); bladder cancer (1); breast carcinoma (1); oral squamous cell carcinoma (1); prostate carcinoma (1).